HIF1A (hypoxia inducible factor 1 subunit alpha)
Diseases named in the same sentence as HIF1A in open-access papers (continued):
Sharing a sentence is not in itself a finding about the gene and the disease.
hepatocellular carcinoma (continued). "For example, Hypoxia was found to upregulate YTHDF1 expression in a HIF-1α dependent manner in hepatocellular carcinoma." (PMID 35197112, 2022). "A link between the hypoxia response and AURKA expression was first uncovered by a group that observed increased AURKA mRNA levels upon hypoxia in HepG2 hepatoma cells, and this occurred via Hypoxia-Inducible Factor 1 (HIF-1α)." (PMID 36067794, 2022). "Aerobic glycolysis acts as a hallmark of hepatocellular carcinoma metabolism and regulates the progression of HCC, such as the PI3K/Akt pathway, AMPK and HIF-1α." (PMID 36353638, 2022). "Two studies reported that HIF-1α expression is suppressed by miR-576-3p at the post-transcriptional level in glioma and hepatocellular carcinoma." (PMID 35712504, 2022). "Especially PPARG was shown to be activated under hypoxic conditions in correlation with HIF1A in lung cancer and hepatocellular carcinoma." (PMID 36064320, 2022). "By contrast, has-circRNA-403658 (cZNF292) is a HIF1α-induced circRNA in bladder cancer, however, it serves as a HIF1α-independent circRNA in hypoxic hepatoma cells." (PMID 35915091, 2022). "In hepatocellular carcinoma cells, NF-κB and HIF-1α pathways are usually in an activated state, especially under hypoxic conditions." (PMID 35178457, 2022). "Hypoxia enhances the stemness of hepatocellular carcinoma cells and hepatocarcinogenesis by enhancing the deSUMOylation of HIF-1α by SENP1 and increasing the stability and transcriptional activity of HIF-1α." (PMID 35392171, 2022). "Recently, the disubstituted adamantyl derivative LW1564 has been reported to impair tumor metabolism by suppressing HIF-1α accumulation, thereby inhibiting the tumor growth of hepatocellular carcinoma cells in vitro and in vivo." (PMID 36551540, 2022). "AFP can activate the PI3K/AKT signalling, stimulates the transcription cofactor mTOR, STAT3, HIF‐1α and Bcl‐2, which regulates the expression of oncogenes, as well as promotes angiogenesis and the growth of the hepatoma cells." (PMID 36181321, 2022). "As an active protein kinase, PKM2 promotes hepatocellular carcinoma cell proliferation by upregulating HIF-1α, Bcl-xl and Gli1 expression." (PMID 36686771, 2022). "Functionally, it promoted hepatocellular carcinoma via SUMOylating HIF-1α to upregulate vascular endothelial growth factor." (PMID 36292141, 2022). "Recent studies have shown that the lncRNA PAARH promotes hepatocellular carcinoma (HCC) angiogenesis by activating HIF-1α/VEGF signaling." (PMID 35958561, 2022). "In studies of hepatocellular carcinoma, bufalin was found to down-regulate HIF-1α expression by inhibiting the PI3K/AKT/mTOR signaling pathway, and also to reduce cell invasion by inhibiting the TGF-β-induced EMT process." (PMID 36139386, 2022). "Under hypoxic conditions, HIF-1α was essential for NDRG1 transcription in Hepatocellular carcinoma (HCC) cells." (PMID 36497221, 2022). "USP22 promotes the stemness and glycolysis of hepatocellular carcinoma cells induced by hypoxia by deubiquitinating and stabilizing HIF-1α." (PMID 35392171, 2022). "In several cancer cell types (i.e., colon, cervical and hepatocellular cancer cells), another hypoxia-induced mechanism that leads to G0/G1 and S-phase accumulation is the HIF-1α dependent down-regulation of CDC25A protein level." (PMID 34539584, 2021). "Some years later, the connection between the OSM and HIF-1α pathway was provided by a study demonstrating that OSM was able to upregulate HIF-1α and downstream signaling in hepatocytes and hepatoma cells." (PMID 34359934, 2021).
hepatocellular carcinoma (continued). "KN-62, a pharmacological inhibitor of CaMK2, specifically and effectively suppressed protein synthesis and the functional activity of hypoxia-inducible factor (HIF)-1α in hepatoma cells during hypoxia." (PMID 34193145, 2021). "Among known α-subunits, HIF-1α and HIF-2α have been shown to regulate occurrence of hepatocellular carcinoma, while HIF-3α has generally been associated with inhibition of HIF-1α and HIF-2α activities." (PMID 34307125, 2021). "NDUFA4L2 reportedly acts as an oncogene; notably, it is a direct transcriptional target of HIF-1α in hepatocellular carcinoma, clear cell renal cell carcinoma, lung cancer, and colorectal cancer." (PMID 33828084, 2021). "We demonstrate that Selinexor decreases nuclear HIF-1α protein levels in human hepatoma Hep3B cells and human osteosarcoma U2OS cells under hypoxic conditions." (PMID 33856525, 2021). "STGPT repressed N-nitrosodiethylamine-induced murine hepatocellular carcinoma progression by inhibiting HIF-1α via the interference with the AKT-AMPKα-mTOR axis and the interruption of IKKβ, P38α, and ERK1/2 signals as well." (PMID 35095479, 2021). "Experimental evidence from research into a hepatocellular carcinoma cell line has shown that HIF-1α mediates vasodilator-stimulated phosphoprotein (VASP) overexpression at the transcriptional level by directly binding to the promoter of the VASP gene." (PMID 34884541, 2021). "Zhang and colleagues found that under a hypoxic microenvironment, the HIF-1a/IL-1b signaling loop between hepatoma cells and TAMs can promote EMT of cancer cells and metastasis." (PMID 33537099, 2021). "In the Hep3B hepatoma cell line, silencing of SDHB also stabilizes HIF-1α/2α and causes enrichment of functionally diverse genes, including hypoxia-related genes." (PMID 33637686, 2021). "Dysfunction of MOF in hepatocellular carcinoma cells also results in chemoresistance to trichostatin A, sorafenib and 5-fluorouracil via HIF-1α." (PMID 34540836, 2021). "HIF-1α upregulated the expression of Notch1, Notch3 and Notch4 via binding to the hypoxia response elements in their promoter regions in hepatocellular carcinoma cell lines." (PMID 34988077, 2021). "miR-3662 in hepatocellular carcinoma tends to be downregulated, and the high expression of miR-3662 inhibits hepatocellular carcinoma growth by inhibiting HIF-1α." (PMID 34616613, 2021). "In hepatocellular carcinoma, the upregulation of FABP5 enhances hypoxia-inducible factor-1 alpha (HIF-1α) activity, causing lipid metabolism reprogramming, and carcinoma progression." (PMID 34934042, 2021). "Both hepatic carcinoma cell lines were treated with taxifolin for 24 h and then assessed for taxifolin effect on Hif1-α, VEGF and Akt mRNA and protein expression level." (PMID 34113483, 2021). "For instance, silencing TRPC1 is able to inhibit the proliferation of hepatocellular carcinoma cells, decrease the invasion, migration, and proliferation of thyroid cancer cells via reducing HIF-1α expression." (PMID 34642309, 2021). "In hepatocellular carcinoma, the expression of HIF-1α and its target genes LDHA and hexokinase 2 (HK2) is inhibited by balanophorin B under hypoxia, resulting in the suppression of glycolysis in vitro." (PMID 34575983, 2021). "Hypoxia-inducible factor-1α (HIF-1α) have also been reported to be the target of chaetocin in hepatoma, however, this HIF-1α-targeting mechanism does not hold in other cancer cells." (PMID 34776955, 2021). "In hepatocellular carcinoma, andrographolide diminishes the level of HIF-1α and VEGF in vitro and in vivo." (PMID 34575983, 2021).
hepatocellular carcinoma (continued). "YAP can also bind to HIF-1α in the nucleus and sustain HIF-1α protein stability in conditions of hypoxic stress in hepatocellular carcinoma cells." (PMID 33980319, 2021). "In hepatocellular carcinoma and renal cell carcinoma, Cav-1 is induced by hypoxia via hypoxia-inducible factor 1α (HIF-1α), suggesting a possible role of Cav-1 in tumor angiogenesis." (PMID 34287575, 2021). "Activated AKT stimulates the mTOR transcription cofactor and the STAT3 and HIF-1α transcription factors, which regulates the expression of oncogenes, inhibits apoptosis and inhibits autophagy in hepatoma cells as well as promotes the growth of cancer cells." (PMID 33898423, 2021). "Selinexor significantly reduced the intranuclear level of HIF-1α protein in human hepatoma cells Hep3B and human osteosarcoma cells U2OS." (PMID 33856525, 2021). "OPN promotes a CSC-like phenotype in hepatocellular carcinoma cells through binding with αvβ3 integrin and subsequent downstream involvement of NF-κB and HIF-1α." (PMID 33203146, 2020). "It was reported that bufalin suppressed hepatocellular carcinoma invasion and metastasis by targeting HIF-1α." (PMID 32362830, 2020). "The hypoxic microenvironment increases expression of HIF-1α to promote EMT in hepatoma cells and facilitate their migration and invasion." (PMID 32377312, 2020). "HIFs were also reported to promote DENV RNA replication and translation through a HIF-1α dependent mechanism in Huh-7 hepatoma cells." (PMID 33113858, 2020). "Knockdown of SIRT3 in human hepatoma cells confirmed the upregulation in both HIF-1α and LIPIN 1 protein levels, whereas this increase was blunted when cells were exposed to palmitate." (PMID 32912335, 2020). "Data from hepatocellular carcinoma (HCC) models have shown significant correlation between HIF-1α expression and an increased proportion of M2 macrophages." (PMID 33348579, 2020). "In hepatocellular carcinoma (HCC) tissues, both FABP5 and HIF-1α are upregulated, and their expression levels are associated with poor prognosis." (PMID 33128030, 2020). "Our studies find that Nrf2 directly regulates HIF-1α expression under hypoxia conditions to promote cisplatin-resistance in hepatocellular carcinoma cells, providing novel knowledge on drug resistance in the hypoxic tumor micro-environment." (PMID 33290263, 2020). "The researchers have reported that celastrol showed a dose-dependent inhibition of HIF-1α levels under hypoxia induced by CoCl2 in human hepatoma cells." (PMID 32091275, 2020). "Analogously, the PIK3C2α/AKT/HIF-1α/VEGFA pathway regulated by miR-26a plays a role in inhibiting angiogenesis in hepatocellular carcinoma." (PMID 32014012, 2020). "In the diethylnitrosamine (DEN)-induced primary hepatocellular carcinoma rat model, CK downregulated Bclaf1 expression, inhibited the HIF-1α-mediated glycolysis pathway, and affected the proliferation of hepatoma cells." (PMID 33363466, 2020). "PRODH activity can also concur to suppress hypoxia-inducible factor 1 alpha (HIF1α)-mediated signaling by increasing the synthesis of α-KG, in hepatocellular carcinoma." (PMID 32500033, 2020). "Other studies have noted that in hepatoma-derived cell lines, HIF-1α regulates the expression of BHLHE40." (PMID 32577154, 2020). "Subsequent knockdown experiments revealed that this VEGF secretion is regulated through the activation of the ERK1/2/HIF-1α/VEGF pathway following frequent upregulation of UBE2CP3 in hepatocellular carcinoma cell." (PMID 32640630, 2020). "HDAC6 promotes cell proliferation of hepatocellular carcinoma and HIF-1α and VEGFA expression, thereby promoting HIF-1-mediated angiogenesis in hypoxic conditions." (PMID 33109235, 2020). "In hepatocellular carcinoma, activated HIF-1α is indicated to be a downstream regulator of the PI3K/AKT pathway and is accompanied by differences in EMT biomarkers." (PMID 33256814, 2020).
hepatocellular carcinoma (continued). "LncRNA UBE2CP3 promotes angiogenesis in hepatocellular carcinoma cells by activating ERK/HIF-1α/VEGFA signaling." (PMID 32993787, 2020). "Via the HOTAIR/miR-130a-3p/HIF-1α axis, HOTAIR positively regulates HIF-1α expression resulting in enhanced glycolysis in hypoxic hepatocellular carcinoma cells." (PMID 32640630, 2020). "For HIF-1α, a high HIF-1α level is involved in increases in M2 polarization and accelerates hepatocellular carcinoma progression." (PMID 33376580, 2020). "More recent studies are in agreement with these results, reporting that SENP1 increased the stabilization and transcriptional activity of HIF-1α in hypoxia via desumoylation in hepatocellular carcinoma (HCC) and ovarian cancer cells." (PMID 33114748, 2020). "Gong et al21 have found that inhibition of FASN in hepatocellular carcinoma cell lines reduces the migration and invasion by reducing the HIF‐1α/IGFBP1 pathway." (PMID 33164330, 2020). "In contrast, another recent data showed that Sirt1 interacts with HIF‐1α and the deacetylation of HIF‐1α stabilizes HIF‐1α protein expression and promotes its activity using human hepatoma cell lines such as Hep3B, HepG2, and Huh7 cells." (PMID 30614190, 2019). "Later, it was revealed that it suppresses hepatocellular carcinoma through suppressing the STAT3/HIF-1α/VEGF signaling network." (PMID 30871059, 2019). "Under the condition of hypoxia, HIF-1α, which can stimulate the formation of new blood vessels and alleviate the cell hypoxia, can be higher in hepatoma cells and increase the survival of cancer cells." (PMID 30911540, 2019). "Hypoxia-inducible factor-1α (HIF-1α) plays a key role by triggering the transcriptional activation of a number of genes involved in migration, invasion, and angiogenesis in hepatocellular carcinoma (HCC)." (PMID 31239858, 2019). "SBP1 had been reported to inhibit GPX1 activity to promote oxidative stress and reciprocally regulate hypoxia-inducible factor-1α (HIF-1α) in the oxidative stress model of hepatoma cells stimulated by H2O2." (PMID 31019652, 2019). "During hypoxia, hepatocellular cancer cells contained the linc-RoR (regulator of reprogramming), thus decreasing miR-145 and hypoxia-inducible factor 1 alpha (HIF-1α) in recipient cells." (PMID 30781588, 2019). "CDK5 has been demonstrated to stabilize HIF-1α in hepatocellular carcinoma, which is also one of the most vascularized tumors." (PMID 31311512, 2019). "Jiang et al56 discovered that, in hypoxic conditions, NF‐κB expression increased in hepatoma cells, and the Bp50 and p65 NF‐κ subunits bound to the HIF‐1α promoter, thereby increasing transcription." (PMID 31411003, 2019). "In the context of radiation, PX-478 enhances radiosensitivity of prostate carcinoma and hepatoma cells under hypoxic conditions by inhibiting HIF-1α expression." (PMID 30669417, 2019). "For example, CDK5 has been reported to highly express in hepatocellular carcinomas and promote tumor vessels formation though directly stabilizing the HIF-1α, and CDK5 also participated in regulating the migration of prostate cancer cells." (PMID 31311512, 2019). "Decreased immunohistochemical expression of HIF1A in hepatoma xenografts in mice supported the findings." (PMID 30241339, 2018). "The study in hepatocellular carcinoma demonstrated that the HIF-1α/miR-210/HIF-3α feedback circuit plays a regulatory role in TIMP2 suppression." (PMID 29953500, 2018). "An AMPK-independent mechanism of MTF effects was demonstrated in hepatoma cell lines where hypoxia inducible factor 1 subunit alpha (HIF1A) protein accumulation was impaired by MTF-mediated HIF1A protein degradation." (PMID 30241339, 2018). "A critical role of HIF-1α signaling in MDSCs is described in murine cancer models, such as hepatocellular carcinoma (HCC) and in patients with non-small cell lung cancer." (PMID 30425715, 2018).
hepatocellular carcinoma (continued). "Chai and co-workers detected that expression of VEGF-A was inversely correlated with miR-26a-5p expression in hepatocellular carcinoma and that miR-26a-5p modulated angiogenesis of hepatocellular carcinoma through the PIK3C2α/Akt/HIF-1α/VEGFA pathway." (PMID 29483572, 2018). "We used CoCl2 and HIF1-α knockdown to confirm that HIF1-α can induce LOXL2 expression in hepatocellular carcinoma cells in vitro." (PMID 28449718, 2017). "To investigate if HIF1α and HIF2α regulated SPRY2 mRNA and protein levels, we used siRNAs to silence the expression of endogenous HIF1α and HIF2α proteins in the hepatoma cell line Hep3B." (PMID 28196140, 2017). "Treatment with norepinephrine (NE), a ligand of the adrenergic receptor, up-regulated VEGF expression and angiogenesis in an HIF-1α-dependent manner in human breast, prostate, and hepatocellular cancer cells." (PMID 28977888, 2017). "In order to further elucidate mechanism of interaction between MTA1 and HIF-1α, hepatocellular carcinoma cell line HepG2 was employed." (PMID 28589145, 2017). "The present study sought to characterize the involvement of orexin A in glucose metabolism in HepG2 human hepatocellular carcinoma cells, and investigated the role of hypoxia-inducible factor-1α (HIF-1α) in the response." (PMID 28886081, 2017). "Girdin can regulate glycolysis in hepatocellular carcinoma cells through the PI3K/AKT/HIF-1α signaling pathway, which decreases the sensitivity of tumor cells to radiotherapy." (PMID 28810896, 2017). "In the hepatocellular carcinoma Hep3B cell line, exposure to low-dose (0.5 μM) and moderate-dose SAHA (1 μM) caused a decrease in the quantity of HIF-1α and HIF-2α under hypoxic conditions." (PMID 28915577, 2017). "The long non-coding RNA (lncRNA) CPS1-IT1 acts as a co-chaperone, alters Hsp90 and HIF-1α binding affinity and reduces HIF-1α activity in hepatocellular carcinoma." (PMID 29137361, 2017). "Herein, we demonstrate that, in the hepatoma cell line Hep3B, endogenous HIF1α and HIF2α decreased the mRNA levels of SPRY2 with a concomitant decrease in the protein levels of Spry2." (PMID 28196140, 2017). "The purpose of our study is to explore the role of HIF-1α in progression and metastasis of hepatocellular carcinoma by promoting the expression of LOXL2 as well as the potential regulatory mechanism." (PMID 28449718, 2017). "Inhibiting CDK5 activity in hepatocellular carcinoma (HCC) cells prevented angiogenesis in vivo by decreasing the abundance of HIF-1α." (PMID 28077789, 2017). "Knockout of Hif1a sensitized hepatoma cells to etoposide treatment in a transgenic murine model with hepatocyte-specific expression of SV40 large T oncogene, but did not affect the initiation and progression of murine HCCs." (PMID 28493839, 2017). "In contrast, in human hepatoma 3B, fibrosarcoma, and epithelial lung cells HIF1α stabilisation during hypoxia is redox sensitive." (PMID 29123322, 2017). "SSd has a radiosensitizing effect on hepatoma cells under hypoxic conditions by inhibiting HIF-1α expression." (PMID 27951737, 2017). "It has been reported that HIF-1α suppresses hepatocellular carcinoma cell apoptosis through upregulating Bcl-2 and inhibiting the expression and mitochondrial release of Omi/HtrA2, a serine protease involved in capase-dependent apoptosis." (PMID 27094811, 2016). "Mechanistically, our study demonstrated that hypoxia-inducible factor-1α (HIF-1α) played an important role in the antimetastatic effect of bufalin in hepatocellular carcinoma." (PMID 26958938, 2016). "Overexpression of hypoxia-induced factor 1α (HIF-1α) has been shown to be involved in the development and progression of hepatocellular carcinoma (HCC)." (PMID 26621849, 2016).